IL6 (interleukin 6)
Diseases named in the same sentence as IL6 in open-access papers (continued):
Sharing a sentence is not in itself a finding about the gene and the disease.
atherosclerosis (continued). "Patients with both atherosclerosis and ischemia, together with higher levels of HO-1, have also significantly altered markers of metabolic syndrome (BMI, HOMA, HDL-C, TG/HDL-C), systemic inflammation (IL-6), ischemic vascular and myocardial dysfunction (hs-cTnI and NTproBNP)." (PMID 34943105, 2021). "Therefore, elevated levels of CARD8 in atherosclerosis may therefore contribute to increased inflammation in the pathogenesis of atherosclerosis by upregulation of CXCL1, CXCL6, IL-6 and possibly also MCP-1, may aggravate atherosclerosis." (PMID 33154409, 2020). "Although the precise roles of IL-2 in atherosclerosis are not well clarified, substantial research evidences have demonstrated the potent roles of IL-2 in stimulating lymphocytes to produce inflammatory cytokines, such as IL-6, TNF-α, and IFN-γ." (PMID 31379468, 2019). "In addition, NaVO3-mediated IL-6 enhancement and SM22α reduction in the atherosclerotic lesions were suppressed by NAC in a dose-dependent manner, indicating that NaVO3 triggers ROS-meditated IL-6 production to induce atherosclerosis." (PMID 31817202, 2019). "Additionally, it was observed that FCs immunization down-regulated the expression level of atherosclerosis related pro-inflammatory cytokines, including IFN-γ, MCP-1, and IL-6 and enhanced the lesion stability with a significant increase in TGF-β1 level and collagen content." (PMID 30687328, 2018). "VSMCs secrete copious IL-6 under stimulation conditions such as tumor necrosis factor (TNF)-α, IL-1β, platelet-derived thrombin, endothelin I, and lipopolysaccharide that they may be involved in the pathogenesis of atherosclerosis." (PMID 28531207, 2017). "However, it remains to be established whether IL-6 fosters platelet activation, MPA formation and the development of atherosclerotic plaques or is just a surrogate marker for already existing atherosclerosis with ongoing platelet activation." (PMID 25807315, 2015). "Nevertheless, MCP-1 inhibition resulted in decreased TNFα, IL-6, tissue factor and PAI-1 in an inflammation model induced by stress in mice, suggesting a beneficial effect not only in inflammation but also in the prothrombotic state in the presence of atherosclerosis." (PMID 26578976, 2015). "Atherosclerosis, precursor to cardiovascular diseases, is recognised as a chronic inflammatory disease of large arteries, involving cytokines, such as IFN-γ and TNF-α, adhesion molecules, such as ICAM-1 and VCAM-1, and several plasma inflammatory markers, such as hsCRP, IL-6, and fibrinogen." (PMID 26346892, 2015). "Hence, we speculated that cilostazol inhibits the signaling of NF-kB and decreases transcription of different proteins, including ICAM-1, VCAM-1, E-selectin, TNF-α, interleukin-6 (IL-6), AGE, and ligands for RAGE in human atherosclerosis." (PMID 25666934, 2015). "Initially, it has been hypothesized that C. pneumoniae may contribute to atherosclerosis through inflammation, as evidenced by an increased production of inflammatory cytokines (IL1-β, IL-6, IL-8 and TNF-α) and chemokines found in vascular cells involved in the atherosclerotic process." (PMID 25561227, 2014). "IL-6 also induces ICAM-1 expression on endothelial cells and may play a role in development and progression of atherosclerosis; adhesion molecules such as ICAM-1 and VCAM-1 play a significant role in cell recruitment within the intima during atheroma formation." (PMID 25490200, 2014). "EAT secretes various proinflammatory adipokines like interleukin (IL)-1, IL-6, IL-8, IL-10, tumor necrose factor (TNF) α, leptin, macrophage chemoattractand protein 1 (MCP-1), type I plasminogen activator inhibitor (PAI-1), resistin that provide a metabolic milieu that promotes atherosclerosis." (PMID 23133630, 2012).
atherosclerosis (continued). "Thus, the fat-fed, aged Apoe−/− mouse model develops severe atherosclerosis with myocardial hypertrophy, increased interstitial collagen deposition, increased apoptosis and a chronic increase in IL-6 levels without any evidence of myocardial infarction." (PMID 22848603, 2012). "Recently, a significant role in the regulation of the immune response accompanying atherosclerosis has been ascribed to interactions between activated T cells, promoting the expression of systemic inflammatory response factors participating in atherogenesis, such as TNF–α and IL-6." (PMID 22558213, 2012). "Atherosclerosis and NAFLD progression are both accompanied by inflammation development which involves several factors, including various chemokines (monocyte chemoattractant protein 1; MCP-1), cytokines (tumor necrosis factor-α; TNF-α), interleukin-6 (IL-6) and C-reactive protein (CRP)." (PMID 23226761, 2012). "It is of interest to note that in the Canakinumab Antiinflammatory Thrombosis Outcome Study (CANTOS), decreases in IL-6 were associated with the observed clinical benefit both in terms of MACE and cancer, and it is not surprising that IL-6 targeting is now being pursued in atherosclerosis." (PMID 40924496, 2025). "Although hepatocellular carcinoma (HCC) is not a direct cause of atherosclerosis, it can contribute to thrombosis and the establishment of a pro-inflammatory microenvironment, characterized by elevated levels of C-reactive protein (CRP), fibrinogen, and interleukin-6 (IL-6)." (PMID 40936714, 2025). "Finally, inflammation assessed by increased CRP and interleukin-6 (IL-6) levels match OSAS severity and may further contribute to vascular meta-inflammation processes, early atherosclerosis, arterial stiffness, and endothelial dysfunction, ultimately favoring stroke onset." (PMID 40149635, 2025). "Therefore, plasma NAbs for IL6, IL8, and VEGFR1 may have function of downregulating the inflammatory process developed in artery walls and decreased NAbs levels could reduce their protection against atherosclerosis and plaque instability." (PMID 36741286, 2023). "Moreover, in the immune and inflammatory pathways promoting atherosclerosis, activated T cells are involved which are a source of RANKL and pro-inflammatory cytokines (such as tumor necrosis factor α (TNF-α), interleukin-1 (IL-1), and interleukin - 6 (IL-6)), that up-regulate RANKL expression." (PMID 36060948, 2022). "plasma levels of IL-6 correlate with the area of epicardial and abdominal visceral AT in patients with coronary artery atherosclerosis, suggesting a potential effect of these fat depots on the development of atherosclerosis through paracrine rather than systemic effects." (PMID 35207618, 2022). "Our in vitro data also show that F. nucleatum promotes the secretion of inflammatory factors, such as TNF-α, IL-1β, IL-6, and the chemokine MCP-1 during foam cell formation, which suggests that the increased systemic inflammation level induced by F. nucleatum might accelerate atherosclerosis." (PMID 35359716, 2022). "Moreover, this study cannot make a distinction between the timing and the duration of OSM signaling, which may differentially affect atherosclerosis development as previous studies have shown that OSM, like IL-6, can act differently in the acute phase than in the chronic phase." (PMID 33959646, 2021). "IL-1β has not been studied as a biomarker for cardiovascular disease because unlike hsCRP and IL-6, it is difficult to directly measure its levels in the plasma; nevertheless, many studies have been conducted to examine its role as a therapeutic target in atherosclerosis." (PMID 34071276, 2021). "Because of its retrospective design, inflammatory markers related to atherosclerosis (e.g., high-sensitivity C-reactive protein, interleukin-6, and adhesion molecules) were not studied, and a more detailed evaluation of the relationship between CSF and inflammation could not be performed." (PMID 34930134, 2021).
atherosclerosis (continued). "In addition, atherosclerosis is considered to be a chronic inflammatory disease of the large and medium arteries, with changes in pro-inflammatory cytokines such as tumor necrosis factor-alpha (TNF-α),interleukin (IL)-6, and IL-1β, and anti-inflammatory cytokines including IL-10." (PMID 32231564, 2020). "The significant higher level of IL-6, TSH and Leptin in serum in the subjects with PD ≥4 mm further support the notion that, in obese subjects, periodontal disease is part of an systemic inflammation that might, in the long run, lead to atherosclerosis and CVD." (PMID 25884594, 2015). "Unlike IL-6, TNF-α has not yet been shown tohave a dual nature of action in atherosclerosis: that is, it exhibits exclusivelypro-inflammatory effects." (PMID 40160593, 2025). "Consistent with the hypothesis that a significant number of mechanisms underlying atherosclerosis and ACS without SMuRFs remains undiscovered, our study will be the first to elaborate metabolomic and inflammatory biomarkers, such as Lp(a), ApoB and ApoA1 interleukin-6 (IL-6) and suPAR." (PMID 36959584, 2023). "For example, low-dose methotrexate used in cardiovascular inflammatory reduction trial (CIRT) did not lower IL-1β, IL-6, CRP levels, or reduce cardiovascular events in patients with stable atherosclerosis." (PMID 36555898, 2022). "In our study, postprandial plasma CRP, but not haptoglobin, IL-6 or TNF-α, positively correlated with the severity of beginning atherosclerosis." (PMID 21756316, 2011). "In this model, voluntary exercise lowered IL6 and CRP in both diet groups but did not reduce the progression of atherosclerosis in the absence of dietary intervention." (PMID 21359188, 2011). "In a C57BL/6 mouse model of atherosclerosis, the absence of sortilin induced a defect of IL-6 and IFN-γ secretion in activated macrophages and Th1 cells, reducing the inflammatory component of vascular lesions and atherosclerosis, independently of sortilin effect on lipid metabolism." (PMID 30666202, 2018). "In contrast, salusin-α could selectively down-regulate the levels of IL-6 and TNF-α in plasma not MCP-1 and VCAM-1 in the aorta, suggesting little effects of salusin-α on inflammation in atherosclerosis progression." (PMID 24621517, 2014).
viral infection (1,014 papers, 2005 to 2026). "Genetic variations in the IL6 gene, particularly single-nucleotide polymorphisms (SNPs) in the promoter region, can modulate IL-6 expression and potentially influence individual susceptibility to viral infections." (PMID 41745088, 2026). "When RVs overcome this defense line, type I IFNs come into play, leading to an inflammatory response essential for eradicating viral infections but also capable of causing tissue damage mediated by proinflammatory cytokines like IL-6 and IL-1β." (PMID 41301463, 2025). "It has been suggested that high expression of TPO and its associated receptors and elevated IL-6 levels in children with concomitant viral infections are associated with thrombocytosis." (PMID 40632767, 2025). "Zebrafish with Bcl3 deficiency further showed enhanced immune responses and increased susceptibility to both bacterial and viral infections, resulting in significantly elevated levels of pro-inflammatory cytokines il1b, il6, il8, and tnfa." (PMID 41439955, 2025). "Previous studies have also demonstrated that PM2.5 increases susceptibility to bacterial and viral infections by altering levels of pro-inflammatory cytokines (e.g., IL-1β, IL-6, and IFN-β), thereby elevating the risk of frailty." (PMID 41404569, 2025). "IL-6 polymorphisms were associated to viral infection outcomes through affection of IL-6 production." (PMID 39354444, 2024). "IL-6 polymorphisms were associated to viral infection outcomes through affection of IL-6 production and it is an early indicator of tissue injury and systemic inflammatory response." (PMID 39354444, 2024). "This infection leads to increased expression of various genes associated with viral infection, including IL-6 and TLR3." (PMID 38229040, 2024). "In that regard, IL-6-deficient mice have revealed that IL-6 contributes to the pathogenesis of many inflammatory diseases, including bacterial and viral infections, arthritis, experimental colitis, and multiple sclerosis." (PMID 39125976, 2024). "IL6 is a vital innate immune cytokine in protection against other viral infections such as influenza A virus, which can cause pneumonia." (PMID 39040605, 2024). "In our patients, we did not see a strong association between the laboratory parameters associated with the severity of viral disease (such as IL-6 and D-dimer) with TSH." (PMID 38399601, 2024). "For example, the predicted and obtained IL-2 and IL-6 have been associated with the pathogenesis of a viral infection." (PMID 36982944, 2023). "Some studies found that pathogenic T cells were rapidly activated after virus infection, leading to the production of granulocyte-macrophage colony-stimulating factor (GM-CSF) and IL-6." (PMID 36769761, 2023). "IL-6 is a pleiotropic cytokine that exerts both pro- and anti-inflammatory effects in response to tissue damage caused by viral infections." (PMID 37515030, 2023). "Viral infection causes a predominantly LYMresponse, but systemic inflammation, especially high levels of IL-6, paradoxically reduces LYM numbers and consequent cellular immunity." (PMID 37790205, 2023). "Underlying chronic inflammation and/or viral infections create an immune suppressive TME in GC through the production of cytokines including IL-6, IL-11, TNF-α, and transforming growth factor (TGF)-ß35,36." (PMID 37577519, 2023). "It should be noted that in addition to the association between IL-6 and Covid-19, increasing in IL-6 level has been proven to be a good biomarker for disease severity in other viral infections such as hepatitis B virus (HBV)." (PMID 37161412, 2023). "The exposure of RAW264.7 cells to TB100 caused significant induction of both IFN-β and IL6 cytokine levels in ELISA and qRT-PCR formats with just 24 h of exposure, indicating its potential to evoke adaptive antiviral signatures against viral infections." (PMID 37376674, 2023).
viral infection (continued). "IL6 is the major inflammation-associated cytokine that is significantly and robustly upregulated during viral infections, such as SARS-CoV-2, influenza, and RSV infections." (PMID 37474783, 2023). "The development of severe inflammatory manifestations caused by viral infections has been shown to be associated with high levels of IL-6." (PMID 35336914, 2022). "In this regard, it is very interesting that recent reports highlight the importance of IL-6 levels associated with a severe presentation of viral diseases." (PMID 35265721, 2022). "IFN-β administration to NS mice had the strongest pro-inflammatory responses to virus infection with an increase in differential expression of genes associated with inflammation, such as IL-6, TNF-α and IL-8." (PMID 35260752, 2022). "MiR-365-3p can negatively regulate interleukin 6 (IL6) gene expression, a central cytokine during acute phase response and associated with central nervous system protection during viral infections." (PMID 35719399, 2022). "MVP is also related to the production of cytokines such as IL-6 or IL-8 upon viral infection or dsRNA stimulation and is associated with proliferation, apoptosis and chemotherapy resistance in several types of cancers, including colon cancer." (PMID 35681764, 2022). "The specific anti-virus mechanisms of emodin involved vary from virus to virus, while the common denominator is the ability to suppress the inflammatory response caused by viral infection, such as decreasing the expression of IL-6, TNF-α and IFN-β." (PMID 35600857, 2022). "We investigated how IL-6 and macrophages caused the rapid and significant tissue damage following viral infection in Ifnar-/- mice." (PMID 35512020, 2022). "In the present study, we better characterized the mechanism by which the SARS-CoV-2 ORF6 counteracts IFN-β and interleukin-6 (IL-6), which plays a crucial role in the inflammation process associated with the viral infection." (PMID 35746745, 2022). "In another report, IL-6 has been associated with IL-10 in viral infection, showing that IL-6 regulates the maturation of Treg cells and that IL-6 depletion also causes significant ablation of IL-10 in the lungs after RSV infection in an animal model." (PMID 33815363, 2021). "In particular, interleukin 6 (IL-6) plays a pivotal role in the hyper-inflammatory response during the acute phase of viral infection and is associated with disease severity." (PMID 34425707, 2021). "Immunized mice demonstrated cellular response against Gamma and Zeta variants, and after viral infection, reduced viral loads, IL-6 expression, and histopathological outcome in the lungs." (PMID 34960708, 2021). "The secretion of IL-1β and IL-6 has been linked to the recruitment of PMN to the virus infection site, while increased IFN-γ production is indication of T cell response and is involved in the initial monocyte recruitment as well." (PMID 33841400, 2021). "Especially, viral infection caused a tenfold increase of IL‐1β and IL‐6 level in the culture medium from the lower endothelium layer as compared to the group without infection." (PMID 33173719, 2021). "The level of IL-6 in the acute phase of this viral disease is higher in comparison to neuroborreliosis (NB) caused by a bacterium called Borrelia burgdorferi or healthy subjects." (PMID 34638953, 2021). "Old age/existing comorbidities, decreased count of absolute T lymphocytes and raised interleukin-6 levels have been shown to be associated with severe viral infection." (PMID 34138748, 2021). "Gancainin H and liquorice glycide E (from liquorice) act on ACE2, and glycyrin targets IL-6 and GM-CSF, orchestrating multiple signaling pathways to attenuate inflammation and viral infection, thus preventing lung and heart injury caused by SARS-CoV-2." (PMID 33995078, 2021). "IL‐6 deficiency results in the severe reduction of CXCR5+BCL6+ early Tfh cells in vivo within 72 hours of an acute viral infection." (PMID 34032001, 2021).